SACK1A (scaffolding CK1 anchoring protein A)
Description:
Involved in mitochondrial maintenance during adipogenesis. May be acting by playing a role in the maintenance of normal mitochondrial function.
Synonyms: FAM83A; MGC14128; BJ-TSA-9
Tractability: PROTAC: ubiquitination databases record sites on it.
Gene: Protein-coding gene on chromosome 8 (123,178,960 to 123,210,079, forward strand). Ensembl gene ENSG00000147689.
Subcellular location: Cytoplasm
Subcellular location (Human Protein Atlas): Nucleoplasm; Cytosol
Pathways (Reactome):
Signal Transduction: Signaling by EGFR
Gene Ontology:
Molecular function: identical protein binding; phosphatidylinositol 3-kinase regulatory subunit binding; protein binding; protein kinase binding
Biological process: cell population proliferation; epidermal growth factor receptor signaling pathway; positive regulation of adipose tissue development; white fat cell differentiation
Cellular component: cytoplasm; mitochondrion
Genetic constraint (gnomAD): Loss-of-function variants: 21 observed, 24.13 expected, observed/expected ratio (o/e) 0.87, 90% interval 0.62 to 1.25. The upper end of that interval is the gene's LOEUF score, 1.25, which puts it in group 5 of 6, group 1 being the genes least tolerant of losing a copy. Missense variants: 617 observed, 567.08 expected, observed/expected ratio (o/e) 1.09, 90% interval 1.02 to 1.16. Synonymous variants: 270 observed, 245.22 expected, observed/expected ratio (o/e) 1.1, 90% interval 1 to 1.22.
Homologues: Orthologues: chimpanzee FAM83A (99% identical), macaque FAM83A (96% identical), pig FAM83A (84% identical), dog FAM83A (84% identical), mouse Fam83a (82% identical), rabbit FAM83A (82% identical), rat Fam83a (81% identical), guinea pig FAM83A (78% identical), tropical clawed frog fam83a (49% identical). Paralogues in human: SACK1C (32% identical), SACK1G (29% identical), SACK1H (28% identical), SACK1F (27% identical), SACK1B (26% identical), SACK1D (26% identical), SACK1E (25% identical).
Diseases named in the same sentence as SACK1A in open-access papers:
SACK1A is named in the same sentence as 50 diseases in open-access papers, as found by Europe PMC text mining. Sharing a sentence is not in itself a finding about the gene and the disease.
SACK1A shares sentences with these, for which no sentence is quoted: tumor (59 papers); cancer (58); lung carcinoma (35); breast carcinoma (33); pancreatic cancer (30); lung adenocarcinoma (24); cervical cancer (11); bladder cancers (9); hepatocellular carcinoma (6); lymph node metastasis (6); non-small cell lung carcinoma (6); ovarian carcinoma (5); lung squamous cell carcinoma (4); adenocarcinoma (3); COVID-19 (3); head and neck squamous cell carcinoma (3); brain tumor (2); cervical squamous cell carcinoma (2); endocervical adenocarcinoma (2); metastasis (2); pancreatic adenocarcinoma (2); pancreatic ductal adenocarcinoma (2); triple-negative breast carcinoma (2); uterine cancer (2); asthma (1); breast tumor (1); cholangiocarcinoma (1); colon cancer (1); eczema (1); endocrine system disorder (1).
A further 20 diseases each share a sentence with SACK1A in 1 paper.